RN7SL397P (RNA, 7SL, cytoplasmic 397, pseudogene)
Gene: Miscellaneous RNA gene on chromosome 3 (120,121,909 to 120,122,206, forward strand). Ensembl gene ENSG00000244139.
Homologues: Orthologues: chimpanzee Metazoa_SRP (99% identical), macaque Metazoa_SRP (92% identical). Paralogues in human: RN7SL3 (85% identical), RN7SL1 (85% identical), RN7SL2 (84% identical), RN7SL559P (83% identical), RN7SL220P (82% identical), RN7SL769P (82% identical), RN7SL126P (81% identical), RN7SL679P (81% identical), RN7SL296P (81% identical), RN7SL43P (81% identical), RN7SL712P (80% identical), RN7SL28P (80% identical), and 704 more.